SLC7A11 (solute carrier family 7 member 11)
Diseases named in the same sentence as SLC7A11 in open-access papers (continued):
Sharing a sentence is not in itself a finding about the gene and the disease.
tumor (continued). "Moreover, we analyzed the correlation among four-gene signature (FeSig) (BID, TAZ, MT1G, and SLC7A11), downstream hub genes (CPNE7, WNT10B, ADAMTS14, and RUFY4), and immune checkpoints (PD-1, CTLA4, LAG3, and TIGIT) to further discover potential molecular mechanisms of tumor immunity." (PMID 34367965, 2021). "Consequently, tumour cells that require high GSH levels for survival are potentially more sensitive than normal cells to glutaminase inhibitors that prevent glutamine from being converted to glutamate, which would in turn be used by SLC7A11 to import cystine into cells." (PMID 33276631, 2020). "Erianin inhibited the expression of SLC7A11 and GPX4 and activated the JAK2/STAT3 pathway, suppressing tumour growth without harm." (PMID 40916076, 2025). "In order to examine the expression of SLC7A11 in PTC and its potential clinical significance, 86 cases of tumor and corresponding noncancerous tissue from PTC patients were evaluated." (PMID 35721711, 2022). "Regulating the expression of SLC7A11 gene is believed to be a critical, but not the sole, target for FTO to regulate tumor progression and ferroptosis in PTC cells." (PMID 35721711, 2022). "Moreover, in these tumor samples from nude mice, the expression of LAPTM4B positively correlated with expression of SLC7A11, but not GPX4." (PMID 38902268, 2024). "Notably, solute carrier family 7 member 11 (SLC7A11), a critical regulator of GSH homeostasis in tumor cells, was substantially downregulated in the absence of the SNF2L protein." (PMID 39532848, 2024). "Notably, the expression levels of SLC7A11 and GPX4 were related to tumour diameter and distant metastasis but not to age, sex, lymph node metastasis, or pathological differentiation." (PMID 37807410, 2023). "Interestingly, when comparing expression across all tumor samples versus all normal tissue samples, in contrast to SLC3A2 and SLC7A11, GPX4 was not significantly overexpressed in cancer tissues compared to normal tissues across the set." (PMID 33672555, 2021).
cancer (919 papers, 2012 to 2026). A tumor composed of atypical neoplastic, often pleomorphic cells that invade other tissues. "Research has revealed that lower concentrations of SLC7A11 increase susceptibility to ferroptosis, and its elevated expression impedes the onset of liver damage and cancer." (PMID 40860678, 2025). "Elevated levels of SLC7A11 are frequently associated with resistance to ferroptosis, which allows cancer cells to survive despite oxidative stress that would typically induce cell death." (PMID 40535572, 2025). "In the context of cancer, high levels of SLC7A11 have been associated with increased resistance to therapies, as well as enhanced metastatic capabilities." (PMID 41030277, 2025). "Recent studies have shown that SLC7A11 is overexpressed in various cancer types and is associated with poor patient prognosis." (PMID 41249582, 2025). "Dysregulation of SLC7A11 has been implicated in promoting tumorigenesis and metastasis in several cancers, including NSCLC." (PMID 41030277, 2025). "For example, L-selenocystine has demonstrated the ability to exploit the vulnerabilities associated with SLC7A11 overexpression, leading to increased oxidative stress and cell death in cancer cells that depend on this transporter for their survival." (PMID 40535572, 2025). "Cancer cells with mutated RAS have been shown to have increased SLC7A11 transcription, which leads to increased levels of intracellular cysteine and GSH." (PMID 41514908, 2025). "Conversely, certain cancer cells harbouring oncogenic KRAS mutations exhibit elevated levels of SLC7A11 expression along with intracellular cysteine and GSH abundance." (PMID 39354653, 2025). "The complex regulatory mechanisms associated with SLC7A11 underscore its critical role not only in the process of ferroptosis but also within the larger framework of cancer biology and the challenges of therapeutic resistance." (PMID 40535572, 2025). "While SLC7A11 is typically associated with promoting cancer cell survival, under glucose starvation conditions, SLC7A11high cancer cells exhibit a distinct cell death mechanism known as disulfidptosis." (PMID 40012016, 2025). "Dysregulation of SLC7A11 has been implicated in various diseases, including cancer, neurodegenerative disorders, and metabolic disorders." (PMID 39569390, 2025). "Stable SLC7A11 knockdown in cancer-associated fibroblasts (CAFs) reduces tumor incidence, growth, and fibrosis." (PMID 40249927, 2025). "The SLC7A11 expression level and its mutation signature in pan-cancer were also explored, as well as the functional enrichment associated with SLC7A11 and its related genes." (PMID 40978058, 2025). "The proper functioning of SLC7A11 is vital for preventing oxidative damage, and when it is dysregulated, it has been linked to several diseases, including cancer and neurodegenerative disorders." (PMID 40535572, 2025). "Solute carrier family 7, member 11 (SLC7A11), is implicated in ferroptosis, and various malignant tumor therapies regulate its expression." (PMID 39350768, 2024). "Studies have shown that cystine deficiency or SLC7A11-mediated blocking of cystine transport by erastin can lead to ferroptosis in many cancer cell lines." (PMID 38313306, 2024). "For instance, commonly used inducers like RSL3 and Erastin act by directly inhibiting GPX4 and SLC7A11, respectively, but they fail to comprehensively modulate cancer-associated signaling networks." (PMID 39881871, 2024). "Iron metabolism-related genes such as SLC7A11 are upregulated in human cancers and are associated with a poor prognosis in HCC." (PMID 38540172, 2024). "From this perspective, the SLC7A11 gene exhibits increased expression in various human cancer types, causing the inhibition of ferroptosis." (PMID 38539554, 2024).
cancer (continued). "Aside from the γ-glutamyl cycle, cysteine can be also produced from extracellular cystine through the xCT antiporter encoded by SLC7A11, which is known to maintain the cysteine pool in many cancer cells." (PMID 39000280, 2024). "These ncRNAs can target key ferroptosis-related genes such as GPX4, SLC3A2, and SLC7A11, offering novel therapeutic approaches or diagnostic biomarkers for cancer." (PMID 39600338, 2024). "For example, the GLUT1 inhibitor BAY-876 and the GLUT1/3 inhibitor KL-11,743 cause disulfidptosis in cancer cells that express high levels of slc7a11." (PMID 38685115, 2024). "Glucose-deficient cancer cells with high expression of SLC7A11 exhibit disulfide stress due to the accumulation of disulfide material, which disrupts the normal binding of disulfide bonds between cytoskeletal proteins." (PMID 38817361, 2024). "The loss of PTEN function, commonly observed in various cancers, leads to increased expression of SLC7A11." (PMID 39534872, 2024). "Certain studies posit that dysregulation of GPX4, SLC7A11, and Apoptosis-Inducing Factor Mitochondria-Associated 2 occurs in diverse cancers, suggesting their role as prognostic biomarkers for various malignancies." (PMID 38515565, 2024). "They found that mutation of the SOX2 binding site in the SLC7A11 promoter reduces SLC7A11 expression and increases sensitivity to ferroptosis in cancer cells." (PMID 38994937, 2024). "This study revealed that excessive expression of solute carrier family 7 member 11 (SLC7A11) in glucose-deficient cancer cells accelerates nicotinamide adenine dinucleotide phosphate (NADPH) depletion under glucose starvation conditions." (PMID 38185671, 2024). "This occurs through the prevention of BTRC-mediated degradation of NFE2L2, which in turn sustains high levels of SLC7A11, thereby reducing the susceptibility of cancer cells to ferroptosis." (PMID 39534872, 2024). "In summary, high expression of SLC7A11 was associated with the expression of immune checkpoint-related genes and poor prognosis in various prevalent cancers." (PMID 38655266, 2024). "Although overexpression of SLC7A11 promotes disulfidptosis, traditionally, its overexpression has been linked to cancer progression and associated with drug resistance." (PMID 38739940, 2024). "So far, there is growing evidence indicating that over-expression of SLC7A11 is a hallmark of various cancer aspects, such as tumorigenesis, proliferation, metastasis, prognosis and resistance to chemotherapy." (PMID 38817361, 2024). "Glutaminase inhibition reduces intercellular degeneration caused by glutamine in cancer cells with high levels of SLC7A11." (PMID 37598126, 2023). "As a ferroptosis-associated biomarker, Slc7a11 has been investigated in many diseases, especially in cancer and its treatment." (PMID 37424906, 2023). "SLC7A11 is upregulated by BRCA1-associated protein 1 (BAP1) inactivation in cancer cells, which increases the uptake of cystine and the synthesis of GSH to develop the growth of cancer by inhibiting ferroptosis." (PMID 37458878, 2023). "Noteworthy, the positive association of cg06690548 (SLC7A11) methylation with cancer outcome suggests the independent predictive role of DNA methylation at a single nucleotide resolution." (PMID 37397501, 2023). "We combined all kinds of human cancers together, and the result indicated that high expression of SLC7A11 was significantly associated with unfavorable OS and RFS." (PMID 36874967, 2023). "Collectively, our data suggest that cell death in SLC7A11-high cancer cells under H2O2 treatment is likely caused by SLC7A11-mediated cystine transport and disulfide accumulation, but not by ROS per se." (PMID 37339981, 2023). "In glucose-deficient SLC7A11-high cancer cells, massive accumulation of disulfide molecules leads to abnormal disulfide bonding between actin cytoskeletal proteins, disrupting their organization and ultimately leading to actin network collapse and cell death." (PMID 37759294, 2023).
cancer (continued). "To further evaluate the clinical significance of our findings in larger cohorts of patients, we analyzed TCGA public database to evaluate associations between SLC7A11 expression and cancer-relevant clinical variables and outcomes." (PMID 38023731, 2023). "Lower expression of SLC7A11 is associated with higher responses of cancer cells to arsenic trioxide, parthenolide, and raloxifene that inhibit the proliferation or migration of RCC cells and are a potential therapeutic strategy for RCC." (PMID 37940859, 2023). "For example, it can hold up cancer progression via binding to the promotor of the gene encoding SLC7A11, restraining SLC7A11 expression and boosting ferroptosis." (PMID 38040696, 2023). "On the other hand, studies have shown that the expression of the glutamate/cystine antiporter SLC7A11 in cancer cells is associated with reduced dependence on glutamine metabolism and increased sensitivity to glucose deprivation." (PMID 37649668, 2023). "xCT (encoded by SLC7A11) is crucial for cancer cell survival, proliferation, and malignant development and has been found to be highly elevated in many human tumors." (PMID 36903458, 2023). "Studies have confirmed that overexpression of GPX4 and decreased expression of SLC7A11 are associated with treatment resistance in certain types of cancer." (PMID 37946181, 2023). "Altogether, these data suggest that it is NADPH depletion associated with cysteine generation that causes SLC7A11-high cancer cell death under conditions of glucose starvation." (PMID 35280777, 2022). "Another tumor suppressor, BAP1, frequently found lost or mutated in cancers, has been shown to repress SLC7A11 expression thereby impairing cystine uptake and promoting ferroptosis in cancer cells." (PMID 35280777, 2022). "Elevated expression of SLC7A11 renders cancer cells more susceptible to glucose limitation due to redox imbalance." (PMID 35053507, 2022). "ATF4 promotes ferroptosis resistance in cancer cells by upregulating SLC7A11 as an adaptive response to cystine deficiency." (PMID 36552652, 2022). "Deficiency in genes responsible for supplying cancer cells with the substrates for de novo glutathione synthesis (SLC7A11, SHMT2, and MTHFD1L), as well as the enzymes required to synthesize glutathione (GCLC and GCLM), augments the activity of eprenetapopt." (PMID 36103522, 2022). "The ATM-mediated down-regulation of SLC7A11 caused by RT is the cause of ferroptosis in cancer cells." (PMID 34996454, 2022). "SLC7A11 has been reported to be overexpressed in cancer and associated with poor prognosis in patients." (PMID 35311457, 2022). "Cancer-associated fibroblasts (CAFs) are highly dependent on SLC7A11, and the removal of SLC7A11 increased ferroptosis of CAFs in PDAC." (PMID 36499358, 2022). "As an essential part of the Xc- system, SLC7A11 has been confirmed to be highly expressed in some cancer cells and can attenuate the ferroptosis effect caused by erastin." (PMID 36008384, 2022). "The loss of SLC7A11 and SLC3A2 has been shown to promote cancer cell survival under glucose starvation conditions and SLC7A11 overexpression promotes glucose starvation-induced cell death and vice versa." (PMID 35280777, 2022). "Cox regression analysis of 33 cancers showed that SLC7A11 expression was significantly associated with worse OS in seven cancers, including KIRP, LIHC, LUAD, MESO, OV, UCEC, and UVM (p < 0.05)." (PMID 36267158, 2022). "And on top of that, we unveiled the correlation of SLC7A11 predicting poor prognoses in various cancer types and association with multiple IC genes in the pan-cancer analysis." (PMID 36267158, 2022).
cancer (continued). "SLC7A11 expression is associated with poor prognosis and drug resistance in cancer and, therefore, represents an important therapeutic target." (PMID 35280777, 2022). "In some cancers, apparent silencing or loss of transsulfase enzymes makes cells more dependent on SLC7A11 regulated cystine uptake pathways." (PMID 34996454, 2022). "High CD44v and SLC7A11 expression are closely associated with the resistance to cisplatin in liver and bladder cancers, and sulfasalazine can eradicate the chemoresistant cancer cells." (PMID 36552652, 2022). "ARID1A-deficient cancer cells appear to present a relatively low profile of SLC7A11 because the SWI/SNF complex recruitment to the promoter of SLC7A11 is dramatically reduced, which results in the impediment of GSH synthesis." (PMID 35884471, 2022). "Although multiple genes, such as ACSL4, PTGS2, NOX1, GPX4, FTH1, and SLC7A11, have been shown to be associated with ferroptosis, it is unclear how ferroptosis is genetically programmed in cancers." (PMID 35321435, 2022). "In the present study, we demonstrated that this upregulated transporter rendered cancer cells susceptible to selenite in the context of glucose deprivation, indicating a double-edge-sword property of SLC7A11 for tumors." (PMID 35053507, 2022). "This causes SLC7A11-high cancer cells to be more dependent on the glucose pentose phosphate pathway (a major provider of NADPH in cells), which in turn is metabolically dependent on glucose." (PMID 35280777, 2022). "Recently, NRF2 and ATF4 deficiency was shown to reduce SLC7A11 levels resulting in improved cancer cell survival under low glucose conditions." (PMID 35280777, 2022). "The mechanisms underlying the differential effect of selenite on SLC7A11 expression between cancer cells and normal cells needs further investigation." (PMID 35053507, 2022). "Similar to SLC7A11 deficiency, we found that erastin treatment or cystine starvation also sensitized cancer cells to ferroptosis induced by class 2 FINs." (PMID 33707434, 2021). "We further analyzed the association between SLC7A11 expression and drug sensitivity during cancer treatment using RNAactDrug database." (PMID 34938318, 2021). "The first involves directly inhibiting SLC7A11 transporter activity, whereas the other relates to targeting SLC7A11-associated metabolic vulnerabilities (glucose or glutamine dependency) in cancer." (PMID 33000412, 2021). "For example, SLC7A11 was negatively associated with activated T cells in most cancer types; however, its mRNA level was positively correlated to infiltrated activated T cells in KIRP and UVM." (PMID 34938318, 2021). "This was first proved by the study that immunotherapy-activated CD8+ T lymphocytes can induce ferroptosis in cancer cells by downregulating SLC7A11 and SLC3A2, encoding subunits of system Xc–." (PMID 34568341, 2021). "Third, our study analyzed the association between SLC7A11 expression and potential response to immunotherapy in pan-cancer level, which also brought much valuable information." (PMID 34938318, 2021). "The tumor suppressor BRCA1-associated protein 1 inhibits the growth of cancer cells by regulating the expression of SLC7A11, and its effect is similar to Erastin." (PMID 34869391, 2021). "On the other hand, while this study systematically analyzed the role of SLC7A11 in cancers’ prognosis and immune signatures, the underlying mechanism still needs further investigation by future laboratory research." (PMID 34938318, 2021). "To further explore the function of SLC7A11 in cancer biology, we performed a GSEA to investigate which signal pathways were altered along with differential expression of SLC7A11 in cancers whose prognosis was associated with SLC7A11." (PMID 34938318, 2021).